IL1B (interleukin 1 beta)
Diseases named in the same sentence as IL1B in open-access papers (continued):
Sharing a sentence is not in itself a finding about the gene and the disease.
pneumococcal infection (31 papers, 2010 to 2026). Infections with bacteria of the species streptococcus pneumoniae. "The role of IL-1 signaling in containing the pneumococcal infection was highlighted by the observation that mice deficient in IL-1β had a significantly higher bacterial load in the nasopharynx and lungs." (PMID 36816580, 2023). "Unfortunately, patients receiving IL-1β or inflammasome inhibitors are reported to be at a disproportionate risk to experience invasive bacterial infections including pneumococcal infections." (PMID 33424869, 2020). "Since it has been shown that IL-1β is required for resistance to pneumococcal infection, we investigated the mechanism underlying PLY-induced IL-1β further." (PMID 21085613, 2010). "In another study, pneumococcal infection was shown to trigger the release of IL-1β following the induction of CXCL1 and CXCL2 in epithelial cell." (PMID 38664730, 2024). "These IL-1β and TNFα play a major role in stimulating NF- kβ activation in the pulmonary epithelium and have been observed in most cases of pneumococcal infection." (PMID 38234660, 2024). "Pneumococcal infection of air-liquid interface cultures increases the production of inflammatory cytokines IL-1β and TNF." (PMID 35044807, 2022). "Taken together, these results suggested that H9N2 virus infection reduced production of KC and MIP-2 but promoted IL-1β production after pneumococcal infection at 14 dpi." (PMID 33722928, 2021). "Studies on pneumococcal infections of mouse peritoneal neutrophils indicate that NLRP3 inflammasome is mainly responsible for IL-1β secretion, while the AIM2 and NLRC4 inflammasomes are dispensable in these type of immune cells." (PMID 33424869, 2020). "In our study however, both TNF-α and IL-1β were upregulated in the lungs of gut microbiota-disrupted mice compared to the undisrupted controls after pneumococcal infection." (PMID 30562386, 2018). "Cytokine networks involved in pneumococcal infections are incompletely understood but IL-1β has been shown to regulate CXCL8 release from epithelial cells in reponse to S. pneumoniae and would be an interesting target for future study." (PMID 27430279, 2016). "In contrast, the release of IL-1β was remarkably elevated during pneumococcal infection and high levels of the cytokine was observed at 8 h post-infection." (PMID 26683708, 2015). "In the lungs and central nervous system, pneumolysin induced IL-1β and cell death have been shown to contribute to the inflamed tissue state and the recruitment of immune cells during pneumococcal infection." (PMID 25232870, 2014). "IL-1β plays a key role in promoting IL-17A and was previously shown to mediate protection against pneumococcal infection." (PMID 21085613, 2010). "The canonical cleavage and process of pro-IL-1β to mature IL-1β is catalyzed by caspase-1; thus, we tested whether NanA promotes caspase-1 activation upon pneumococcal infection." (PMID 33777832, 2021). "The noncanonical caspase-8 may also contribute to the NanA-mediated excessive IL-1β production, although further experiments will be required to delineate the role of caspase-8 in IL-1β production upon pneumococcal infection." (PMID 33777832, 2021). "Firstly, CXCL1 release, together with that of IL-1β and IL-6, plays a central role in Nφ mobilization from the bone marrow, in Nφ activation and in the control of bacterial dissemination in the lung after pneumococcal infection." (PMID 33042124, 2020). "The increased susceptibility to respiratory infections in patients treated with anti–IL-1 might be explained by the fact that IL-1β seems to play a role in the resistance to Streptococcus pneumoniae infection." (PMID 32655539, 2020). "Additionally, NLRP3 inflammasome-dependent release of IL-1β is critical for neutrophil antibacterial responses to Streptococcus pneumoniae infection in the lungs." (PMID 31586037, 2019).
pneumococcal infection (continued). "Since autophagy began to increase within 30 min after S. pneumoniae infection and remained elevated up to 4 h, autophagy might play a role in degrading pro-IL-1β and regulating low levels of IL-1β in the initial phase of pneumococcal infection." (PMID 26683708, 2015). "Similarly, in a lethal post-influenza pneumococcal infection mouse model, TSA (1 mg/kg administered 1 h after pneumococcal infection and continued daily throughout the course of the experiment) significantly decreased IL-1β in serum 36 h after pneumococcal infection." (PMID 36412793, 2022). "In the present study, the TLR4-deficient mice had lower TNF-α and IL-1β levels and decreased pulmonary resistance after S. pneumoniae infection compared to wild-type mice, indicating that the TLR4 pathway mediates the immune response against pneumococcal infection." (PMID 30562386, 2018). "Pneumococcal infection can enhance the concentrations of TNF, IL-1β, IL-6, IFN-γ, and IL-10 in the respiratory tract and blood of immunocompetent well-nourished mice, while in protein-malnourished the levels of those immune mediators are significantly lower." (PMID 40507039, 2025). "Given that ATF3 also plays an important role in NLRP3 inflammasome-dependent IL-1β secretion, these data support the idea that ATF3 is an important inflammatory factor in early pneumococcal infection." (PMID 30214444, 2018). "In addition, both immunomodulatory CRL431 and CRL1505 strains improved the production of TNF, IL-1β, IL-6, and IFN-γ in the respiratory tract compared to malnourished and BCD-treated mice, after the pneumococcal infection." (PMID 40507039, 2025). "Our results showed that the production of KC, MIP-2, IL-10, IL-6, and IL-1β did not significantly change when bacterial loads were similar in the lungs of dually infected mice and S. pneumoniae-infected mice after pneumococcal infection at 7 dpi." (PMID 33722928, 2021). "At day 7 post-pneumococcal infection, circulating TNFα and IL-1β were not significantly different across the groups." (PMID 29980196, 2018). "Taken together, our results demonstrate that S. pneumoniae D39-induced ROS generation activates autophagy at 4 h post-infection and also induces the production of IL-1β and the release of LDH at the late phase (8 h) of pneumococcal infection, leading to cell death." (PMID 26683708, 2015). "In addition, the production of IL-10, IL-6, and TNF-α did not significantly change, notably in contrast to IL-1β, which was significantly enhanced after pneumococcal infection at 14 dpi in our study." (PMID 33722928, 2021). "Studies using naive mice have also shown elevated levels of IL-6, IL-1β, MCP-1, MIP-1, MIP-2 and KC in lung tissue starting at 24 hours post challenge in animals that do not control pneumococcal infection." (PMID 29360883, 2018).
bipolar disorder (30 papers, 2011 to 2026). A disorder of the brain that causes unusual shifts in mood, energy, activity levels and the ability to carry out day-to-day tasks. "Bipolar disorder has mainly been associated with polymorphic variants of the IL1B gene." (PMID 37510364, 2023). "IL-1β has been found to be associated with Post-Traumatic Stress Disorder and bipolar disorder." (PMID 36061386, 2022). "Meta-analyses have shown higher levels of pro-inflammatory and anti-inflammatory cytokines, TNF-α, IL-1β, IL-6, IL-4, and IL-10 in patients with bipolar disorder compared to controls at baseline." (PMID 36704001, 2022). "Subjects with bipolar disorder also display increased CSF IL-1β and the highest levels were observed in patients with a history of psychosis." (PMID 33976392, 2021). "In bipolar disorder, increased CSF levels of IL-1β have also been observed among euthymic patients with a life-time history of psychotic episodes." (PMID 33976392, 2021). "In bipolar disorder, cortical mRNA and protein levels of IL1β and IL1 receptor 1 (IL1R1) are elevated." (PMID 34911938, 2021). "In bipolar disorder, protein and mRNA levels of neuroinflammatory markers (IL-1β, IL-1R, MYD88, NF-kB1) and of activated microglia and astroglial markers (GFAP, NOS2, c-Fos, and CD11b) also were significantly higher than in control cortex." (PMID 25329999, 2014). "Moreover, baseline levels of pro-inflammatory cytokines (IL-12, IL-1β) may predict the response of depressive symptoms to CBT in youth with bipolar disorder or MDD." (PMID 33041996, 2020). "Individuals with bipolar disorder presented significantly higher levels of CK-MB (p = 0.0016), CRP (p < 0.0001), IL-6 (p = 0.0198), and IL-1β (p = 0.0067)." (PMID 41750331, 2026). "The NGF, FGF2, NT-3, BDNF, IL-1-β, and dopamine factors also indirectly impact the action of GSK-3β in bipolar disorder." (PMID 37569304, 2023). "Ex vivo studies using peripheral blood monocytes from patients with bipolar disorder have also shown that lithium reduces expression of inflammatory genes (IL-6, TNF, CXCL2) and decreases IL-6 and IL-1β production." (PMID 36704001, 2022).
skin infection (30 papers, 2012 to 2025). An inflammatory process affecting the skin, caused by bacteria, viruses, parasites, or fungi. "IL-1β-deficient mice have demonstrated the importance of IL-1β in neutrophil infiltration and deep S. aureus skin infections." (PMID 29667111, 2018). "In contrast, investigations on Mlkl-deficient mice in the context of skin infection or gram-positive sepsis revealed that Mlkl−/− mice had higher bacterial loads, an inability to limit interleukin-1β (IL-1β) production, and excessive inflammation." (PMID 29606984, 2018). "It has been reported that mice deficient in IL-1β or IL-17 are more susceptible to S. aureus skin infections due to a defect in neutrophil recruitment." (PMID 24098366, 2013). "To investigate whether these PRRs contributed to IL-1β production and neutrophil recruitment during a S. aureus skin infection in vivo, we inoculated wt mice and mice deficient in TLR2, NOD2 or FPR1 with S. aureus." (PMID 23209417, 2012). "Thus, we evaluated TLR2-, NOD2-, or FPR1-deficient mice in response to S. aureus skin infection and found that each of these mice had impaired IL-1β production and neutrophil recruitment after S. aureus skin infection." (PMID 23209417, 2012). "Therefore, in addition to having higher in vivo bacterial burden, mice deficient in TLR2, NOD2 and FPR1 also had decreased IL-1β production and neutrophil recruitment during a S. aureus skin infection in vivo." (PMID 23209417, 2012). "Female mice have been shown to be protected from dermonecrosis in a model of invasive MRSA skin infection due to reduced expression of genes associated with the NLRP3 inflammasome (Nlrp3 and Il1β) compared to males." (PMID 40197396, 2025). "In a Staphylococcus aureus skin infection model, IL-17A/F−/− mice had reduced IL-1α, IL-1β, and TNF-α,39 suggesting that IL-17 regulates these proinflammatory mediators." (PMID 39504049, 2024). "Neutrophils have been shown to be an essential component of the innate immune system involved in the control of Staphylococcal infections, and neutrophil-derived IL-1β is sufficient for immunity against S. aureus skin infection." (PMID 37577369, 2023). "The NLRP3 inflammasome was found to promote IL-1β activation at the site of S. aureus skin infection in mice by mediating neutrophil recruitment to the site of skin infection." (PMID 35878202, 2022). "The involvement of inflammasome-mediated IL-1β in S. aureus clearance in a mouse skin infection model and in a short-term infection of osteoblastic cells was previously demonstrated by our team." (PMID 35531332, 2022). "Neutrophil recruitment prompted by IL-1β is known as a physiological requirement for the clearance of S. aureus skin infections." (PMID 31156635, 2019). "Further experimentation will be required to uncover the precise mechanism leading to reduced tissue destruction in the presence of IL-1β neutralizing therapies during GAS skin infection." (PMID 30018884, 2018). "It was shown in models of skin infection or sepsis that Mlkl−/− mice had high bacterial loads, an inability to limit interleukin-1β (IL-1β) production, and excessive inflammation." (PMID 29606984, 2018). "In the current study, we used gene expression analysis and noninvasive in vivo imaging to determine the functional and temporal kinetics, cellular sources and mechanisms by which IL-1β induces neutrophil abscess formation during a S. aureus skin infection." (PMID 23209417, 2012). "The increased lesion sizes, higher bacterial burden and impaired IL-1β production in TLR2- and NOD2-deficient mice in response to S. aureus skin infection is consistent with previously published studies from our laboratory and others." (PMID 23209417, 2012). "Since in vivo fluorescence imaging demonstrated that IL-1β production was detected shortly after infection, histological evaluation of skin lesions at 4 and 24 hrs after S. aureus skin infection in pIL1-DsRed mice was performed." (PMID 23209417, 2012).
skin infection (continued). "Future studies will be necessary to further dissect the mechanism by which neutrophil-derived IL-1β contributes to host defense during a S. aureus skin infection." (PMID 23209417, 2012). "The reduced IL-10 levels could be allowing amplified NLRP3 activation and IL-1β production during S. aureus skin infection." (PMID 38973612, 2024). "IL-17A, IL-1α, and IL-1β are believed to be protective during mouse MRSA skin infections." (PMID 33573328, 2021). "As a result, ASC-/- or IL-1β-/- mice fail to recruit neutrophils and other phagocytes to infectious foci, and develop significantly enlarged lesions in an experimental model of S. aureus skin infection." (PMID 33552085, 2020). "Data from our in vivo studies demonstrated that IL-1β is robustly induced during GAS skin infection in both an SLS-dependent and independent manner, and that inhibition of this inflammatory cascade leads to reduced skin lesion formation early in the infection process." (PMID 30018884, 2018). "However, wt PMN→IL-1β−/− mice had lesion sizes and in vivo bioluminescence signals that were similar to normal wt mice, indicating that neutrophil-derived IL-1β is sufficient for host defense against the S. aureus skin infection." (PMID 23209417, 2012). "Additionally IL-1β production during the S. aureus skin infection was found to be dependent on bone marrow-derived cells rather than resident skin cells." (PMID 23209417, 2012). "It is known that IL-1β produced at the site of S. aureus skin infection promotes neutrophil recruitment by inducing neutrophil-attracting chemokines and granulopoiesis factors directly via activating IL-1R/MyD88-signaling and indirectly through the production of IL-17 by T cells." (PMID 23209417, 2012). "Furthermore, there was substantial DsRed fluorescence signal on day 1 during our in vivo S. aureus skin infection and at this time point we previously found that IL-1β was detected from the infected skin by ELISA and that both pro-IL-1β and cleaved IL-1β were detected by immunoblotting." (PMID 23209417, 2012). "Thus, although IL-1β-producing neutrophils are sufficient for neutrophil recruitment during a S. aureus skin infection, neutrophil recruitment during sterile inflammation is mediated by IL-1α, IL-1β or both IL-1α and IL-1β, depending on the anatomical site and the type of inflammation." (PMID 23209417, 2012). "In skin infection models, the cGAS-STING antagonizes the TLR signaling pathway, suppressing the production of the key inflammatory cytokine IL-1β and neutrophil recruitment." (PMID 40697819, 2025). "For example, keratinocytes infected with SLO-deficient mutants of S. pyogenes exhibited reduced production of the proinflammatory cytokines IL-1β, IL-6 and IL-8 compared to wildtype S. pyogenes, and SLS can induce the production of IL-1β during skin infection." (PMID 38452154, 2024). "More recently, MG extract is shown to possess antibacterial activity against S. aureus and dramatically downregulate the expression of TH1 cytokines, namely TNF-α, IL-6, and IL-1β, via the TLR-2 pathway in a skin infection model of mice." (PMID 30959963, 2019). "Upon LTA recognition (e.g., in diseases such as colonization and infection of the skin), the NF-κB signaling pathway is activated, leading to the expression of various pro-inflammatory cytokines (TNF-α and IL-1β)." (PMID 29643997, 2018). "We investigated the immune-modulatory activity of celecoxib in MRSA skin infection by measuring the levels of the inflammatory cytokines IL-6, TNF-α, IL-1β, and MCP-1 using ELISA." (PMID 26284040, 2015). "Furthermore, ebselen has been shown to exhibit potent anti-inflammatory activity in two rodent models of MRSA skin infection reducing the expression of key cytokines (TNF-α, IL-1β, and IL-6) that impair wound healing." (PMID 33617589, 2021). "The two strains induced significant difference in IL-1β production at skin infection sites; however, the difference may not be a game changer for the following reasoning." (PMID 26047469, 2015).